VEGFA (vascular endothelial growth factor A)
Diseases named in the same sentence as VEGFA in open-access papers (continued):
Sharing a sentence is not in itself a finding about the gene and the disease.
ovarian carcinoma (continued). "As for the target relation between miR-205 and vascular endothelial growth factor A (VEGFA), a previous study has mentioned that miR-205 was up-regulated in ovarian cancer cells exposed to VEGF, and miR-205 promoted the invasion and proliferation of ovarian cancer cells." (PMID 31719795, 2019). "HIF1α expression did not correlate with either VEGFA/B or MVD, as previously reported for a small cohort (n = 60) of ovarian cancer cases." (PMID 34680301, 2021). "Bioinformatic analysis results show that IGFBP7 is closely correlated with VEGFA protein, but no scientific reports on IGFBP7 and ovarian cancer are currently available." (PMID 24349832, 2013).
colorectal cancer (798 papers, 2002 to 2026). A primary or metastatic malignant neoplasm that affects the colon or rectum. "In colorectal cancer cell lines, NF-κB signaling has been implicated in promoting B7-H3-induced tumor angiogenesis by upregulating vascular endothelial growth factor A (VEGFA), while silencing B7-H3 resulted in the inhibition of NF-κB phosphorylation." (PMID 40214484, 2025). "In a study on colorectal cancer, miR-16-5p was implicated as an oncogenic agent which functioned via the VEGFA/VEGFR1/Akt signaling axis." (PMID 36984512, 2023). "Colorectal carcinoma cells secrete VEGFA, which stimulates tumor-associated macrophages to produce CXCL1 in the primary tumor." (PMID 34907282, 2021). "The clinical impact of VEGFA gene polymorphisms was recently examined in patients with advanced colorectal cancer treated with bevacizumab in association with chemotherapy." (PMID 33238394, 2020). "lncRNA PVT1 has been implicated in the progression of colorectal cancer via the VEGFA-AKT axis." (PMID 40225268, 2025). "Moreover, the secretion of VEGFA by colorectal cancer cells induces tumor-associated macrophages to produce CXCL1 and attract MDSCs, leading to the formation of a premetastatic niche that facilitates the development of liver metastases." (PMID 38555418, 2024). "Therefore, the finding that aberrant splicing of a translation regulator can modulate differential expression of VEGFA variants certainly adds a new layer of complexity to the angiogenic profile of colorectal cancer and their resistance to antiangiogenic therapy." (PMID 26273588, 2015). "Using VEGFA+TC signature genes, we performed unsupervised clustering analysis on colorectal cancer patients from the TCGA database." (PMID 40574852, 2025). "The overexpression of VEGFA is closely related to late tumor stage, high postoperative metastasis, and poor clinical outcomes in colorectal cancer." (PMID 40515512, 2025). "The first VEGFA inhibitor, bevacizumab, was introduced in 2004 and used in the treatment of colorectal cancer." (PMID 40316995, 2025). "Analysis of The Cancer Genome Atlas (TCGA) datasets revealed a positive correlation between MED15 expression and the expression of HIF target genes, including ENO1, HK2, and VEGFA, in renal and colorectal cancers." (PMID 39947475, 2025). "miRNA associations were stronger with hyperlipoproteinemia and vascular disease, while VEGFA displayed more promising results in colorectal cancer and micro- and macrovascular conditions." (PMID 40427019, 2025). "As a stimulator of VEGFA production in tumors, IL-17A has been identified as angiogenesis-promoting in several types of cancer, including non-small-cell lung cancer and colorectal cancer." (PMID 38515019, 2024). "In colorectal cancer, the inhibitory effect of emodin on VEGFA achieved through targeting long-chain acyl-CoA synthetase 4 (ACSL4)." (PMID 38687357, 2024). "In colorectal cancer cells, miR-125a-5p targets VEGFA, thereby inhibiting cell proliferation, migration, and invasion." (PMID 38914670, 2024). "Conversely, angiogenesis in colorectal cancer can be directly promoted by upregulating VEGFA expression." (PMID 37511521, 2023). "Examples of targets used in FME are epidermal growth factor receptor (EGFR, overexpressed in colorectal cancer) and vascular endothelial growth factor A (VEGFA, present in early stages of colorectal neoplasms and Barrett’s dysplasia)." (PMID 35764908, 2023). "M6A modification facilitated the stability of VEGFA by preventing its mRNA degradation in colorectal cancer." (PMID 37229206, 2023). "The ZFAS1 is involved in colorectal cancer progression by inducing vascular endothelial growth factor A (VEGFA), which is one of the important inducers of angiogenesis in tumors." (PMID 36770654, 2023). "FOXD1 upregulates vascular endothelial growth factor A (VEGFA), which accelerates tumor angiogenesis in colorectal cancer." (PMID 37563111, 2023).
colorectal cancer (continued). "ZFAS1 was shown to regulate colorectal cancer progression by interacting with the miR-150-5p/VEGFA axis." (PMID 35112985, 2022). "In this study, we found a high expression of CAVIII in human colorectal cancer tissues and a significant increase in VEGFA, a key protein for vascular neovascularization." (PMID 35625769, 2022). "In this study, TMAO induced colorectal cancer cell proliferation and produced higher vascular endothelial growth factor A (VEGFA) levels in vitro." (PMID 35832644, 2022). "A study on colorectal cancer focused on the retrospective analysis of the relationship between VEGFA, its receptor and clinicopathology." (PMID 33869051, 2021). "Recently, upregulation of PGRN in colorectal cancer has been shown to be correlated with tumor proliferation and vascular endothelial growth factor A (VEGF-A) expression, as well as increased microvessel density." (PMID 33411849, 2021). "A recent study indicated that lncRNA PVT1 promotes the tumorigenesis of colorectal cancer by stabilizing miR-16-5p and interacting with the VEGFA/VEGFR1/AKT axis." (PMID 34336125, 2021). "ZFAS1 has been shown to promote colorectal cancer progression through competitively binding to miR-150-5p and upregulation of VEGFA." (PMID 34703899, 2021). "Recent studies have shown that B7H3 promoted angiogenesis via inducing the expression of VEGFA in both pancreatic and colorectal cancers." (PMID 34079802, 2021). "miRNA-140-5p inhibits the progression of colorectal cancer by targeting vascular endothelial growth factor A and mediates the inhibition of Smad2 and autophagy to inhibit the survival and invasion of colorectal cancer stem cells." (PMID 33628799, 2021). "Studies have reported that hypoxia can promote disease development and metastasis by activating the HIF1α/VEGFA pathway in breast and colorectal cancer." (PMID 34610581, 2021). "circ-0056618 acts as a sponge molecule, adsorbs miR-206, up-regulates the expression of CXCR4 and VEGFA in colorectal cancer, and promotes cell proliferation, migration and angiogenesis." (PMID 34616746, 2021). "We have already conducted a clinical retrospective study on colorectal cancer, demonstrating that the VEGFA score is correlated with patient recurrence free survival and with cancer specific survival." (PMID 31936310, 2020). "In our previous study, ETV5 mediated-angiogenesis was demonstrated to be dependent upon the PDGF-BB/PDGFR-β/Src/STAT3/VEGFA pathway in colorectal cancer (CRC)." (PMID 33099574, 2020). "In colorectal cancer progression, miR-150-5p was discovered to act as a suppressor via targeting VEGFA." (PMID 33146672, 2020). "Previous studies have shown that the expression of VEGFA in human CRC tissues is often down-regulated, miR-150-5p, miR-1249, and microRNA 452 can all regulate the expression of VEGFA and promote the progression of colorectal cancer." (PMID 33537240, 2020). "We found that all hepatoma cells examined have higher levels of VEGFA expression than colorectal cancer (CRC) cells." (PMID 32131390, 2020). "Bevacizumab, a monoclonal antibody against soluble VEGFA, is an approved and commonly administered anti-angiogenic drug in patients with metastasized colorectal cancer (mCRC)." (PMID 32087735, 2020). "It suggests that other factors, very likely of somatic nature and/or less heritable, control the variability of mRNA levels of VEGFA in the tumor of colorectal cancer patients." (PMID 30397360, 2018). "IL-8 protein was strongly expressed by 231_HM.LNm5 cells in vitro (data not shown) and was shown previously to compensate for reduced VEGFA levels to sustain angiogenesis in colorectal cancer xenografts." (PMID 29720474, 2018). "Another study reported that peripheral Treg-cell numbers were diminished by bevacizumab (anti-VEGFA antibody)-containing therapies in patients with colorectal cancer, although TILs were only assessed by IHC." (PMID 30314524, 2018).
colorectal cancer (continued). "In colorectal cancer cells, VEGFA depletion reduces cell survival and enhances chemosensitivity via blockade of AKT and ERK1/2 pathways." (PMID 28383032, 2017). "Here we sought to define the presence of M1/M2 macrophages, PD-1-positive lymphocytes and PD-L1 tumoral and stromal expression in colorectal cancers harboring VEGFA amplification or chromosome 6 polysomy." (PMID 28403223, 2017). "Collectively, these studies support the idea that increases in TBP expression contribute to enhanced VEGFA transcription early in colorectal cancer development to drive tumorigenesis." (PMID 28415573, 2017). "This study aimed to explore the effects of vascular endothelial growth factor A (VEGFA) gene polymorphisms (rs699947 and rs833061) on Bevacizumab (BEV) treatment in colorectal cancer (CRC) patients." (PMID 29285265, 2017). "In colorectal cancer, a novel mechanism for VEGFA isoform expression has been shown to involve the T-cell Intracellular Antigen (TIA-1) activity." (PMID 26273588, 2015). "Levels of the main angiogenic factors, vascular endothelial growth factor-A (VEGF-A) and angiopoietin-2 (Ang-2), are correlated with tumour progression and patient outcome in colorectal cancer." (PMID 21081932, 2011). "PHF20L1 promotes EMT of colorectal cancer cells and increases their invasiveness and metastatic abilities; it also regulates the expression of various angiogenic factors (such as ANGPT2, FGF1, PDGFA, and VEGFA) and promotes angiogenesis in colorectal cancer tissues." (PMID 40723918, 2025). "The m6A “writers” METTL3 and m6A “readers” IGF2BP2/3 were found to participate in the methylation of VEGFA to prevent mRNA degradation, and to promote angiogenesis in colorectal cancer by mimicking the formation of the PI3K/AKT/mTOR and ERK1/2 signaling pathways." (PMID 40316995, 2025). "Reduced GNAI1 expression has been reported in hepatocellular carcinoma, where it is associated with increased tumor cell migration and invasion, as well as in colorectal cancer metastasis, where its loss enhances angiogenesis through activation of JAK2/STAT3 signaling and upregulation of VEGFA." (PMID 41550951, 2025). "B7-H3 upregulates VEGFA expression and angiogenesis by activating the NF-κB pathway in colorectal cancer and it may be a promising target for colorectal cancer treatment." (PMID 38426109, 2024). "Bakshi HA recently found that Crocin, a dietary carotenoid extracted from saffron Himalaya, could inhibit the progression of colon cancer by blocking TNF-α/NF-κB/VEGFA pathway to inhibit angiogenesis and colorectal cancer cell metastasis." (PMID 38687357, 2024). "Additionally, LINC00173.v1 in NSCLC, by downregulating miR-511-5p, and NEAT1 in colorectal cancer, by downregulating miR-205-5p, increased VEGFA expression." (PMID 36012617, 2022). "Additionally, inhibition of miRNA-503-5p promotes colorectal cancer by increasing the expression of vascular endothelial growth factor-A." (PMID 35646947, 2022). "Over 3000 studies have reported that lncRNAs function as sponges to interact with miRNAs; for example, lncRNA ZFAS1 can sponge miR-150-5p to upregulate VEGFA expression to contribute to the progression of colorectal cancer, yet other regulatory mechanisms of lncRNAs are few reported." (PMID 34980188, 2022). "Once knockdown of CAVIII downregulates miR16-5p expression, the combination of miR-16-5p with CAVIII and VEGFA-related signaling pathways may be an effective molecule for future colorectal cancer patients." (PMID 35625769, 2022). "assessed the effects of miR-622, CXCR4, and VEGFA on angiogenesis in colorectal cancer." (PMID 34095461, 2021). "Besides, the expression of VEGFA is significantly upregulated in colorectal cancer cell lines, whereas its expression level in necrotizing enteritis is reported to be significantly reduced." (PMID 34423029, 2021).
colorectal cancer (continued). "MiR-125a-5p inhibits colorectal cancer growth and invasion, VEGFA is a direct target of miR-125a-5p and could reverse the inhibitory effect of miR-125a-5p." (PMID 34977016, 2021). "Finally, further analysis of immunohistochemical experiments found that the level of M2 macrophage infiltration in colorectal cancer tissues with high expression of CCND1 or VEGFA was also significantly increased." (PMID 34922547, 2021). "Similarly, it has been reported that ZFAS1 participates in the progression of colorectal cancer through the miR-150-5p/VEGFA axis." (PMID 34552050, 2021). "A recent study showed that miR‐125asuppresses colorectal cancer progression by targeting VEGFA." (PMID 32697386, 2020). "Moreover, protein biomarkers such as CA19-9, CA 72-4 and carcinoembryonic antigen (CEA), can be used as PRBs of colorectal carcinoma, and plasma vascular endothelial growth factor-A (VEGF-A) can be used as a PRBs for colon cancer." (PMID 32528533, 2020). "miR-150-5p may function as a tumor suppressor in colorectal cancer, making the miR-150-5p/VEGFA axis a potential therapeutic target in colorectal cancer treatment." (PMID 31737629, 2019). "In colorectal cancer, miR-1249-3p may present as a novel therapeutic candidate based on its inhibitory actions in tumor growth, metastasis, and angiogenesis by targeting vascular endothelial growth factor A (VEGFA) and high mobility group AT-hook 2 (HMGA2)." (PMID 31769433, 2019). "Our findings provide insight into the important role of SIRT2 in colon tumour angiogenesis and suggest that SIRT2/STAT3/VEGFA might be a novel prognostic biomarker and a potential therapeutic target for patients with colorectal cancer." (PMID 30584257, 2018). "Anti VEGF strategies have been successful in the clinic for treatment of patients with several cancers, including colorectal cancer (CRC), in the form of Bevacizumab, a monoclonal antibody against VEGFA, and Aflibercept, a recombinant fusion protein blocking VEGFA and VEGFB signalling." (PMID 28536364, 2017). "In addition, EGCG (0.5–10 μM) has been shown to disrupt VEGFA-induced VEGFR2 dimerization in human umbilical vein endothelial cells, and inhibited growth and activation of VEGF/VEGFR axis in human colorectal cancer cells." (PMID 27941682, 2016). "BRAF mutant/MSS cancers are an aggressive cancer type and this may be related to the findings that a BRAF mutation correlates with overexpression of the angiogenic factor, VEGFA, in colorectal cancer." (PMID 23110075, 2012). "The SAM programme typed mRNA of transcripts of the VEGFA, VEGFC, and CCND1 encoding genes to be statistically significant in the compared groups as genes differentiating stages III and IV of clinical progression of colorectal cancer." (PMID 22363883, 2011). "The findings indicate that the ability of farrerol to inhibit the proliferation and migration of colorectal cancer cells may be associated with the induction of G0/G1 phase cell cycle arrest and the regulation of VEGF signaling pathway activation via binding to VEGFA and KDR." (PMID 41415563, 2025). "B7-H3 knockout could downregulate VEGFA to inhibit colorectal cancer angiogenesis." (PMID 38055382, 2023). "Furthermore, in a mouse xenograft model, cell lines with reduced CAVIII expression reduced tumor growth, hemoglobin concentration, and angiogenesis, suggesting that CAVIII/miR16-5/VEGFA may be a new target for the treatment of colorectal cancer." (PMID 35625769, 2022). "Importantly, VEGFA mRNA was detected in EVs from all eight cancer cell lines tested, including colorectal cancer cells (CACO-2, SW480, SW620), pancreatic cancer cells (MiaPaCa-2), lung cancer cells (H1650, H1792), gastric cancer cells (GC38) and liver cancer cells (HepG2)." (PMID 33921957, 2021). "In patients with colorectal cancer liver metastasis, VEGFA could be a prognostic biomarker." (PMID 34226531, 2021).